NOSTRIN (nitric oxide synthase trafficking)
Description:
Multivalent adapter protein which may decrease NOS3 activity by inducing its translocation away from the plasma membrane.
Synonyms: MGC20702; DaIP2
Tractability: Antibody: UniProt places it where antibodies can reach, with high confidence; its Gene Ontology location is reachable by antibodies, with high confidence.
Gene: Protein-coding gene on chromosome 2 (168,786,539 to 168,866,787, forward strand). Ensembl gene ENSG00000163072.
Subcellular location: Cell membrane (Isoform 1); Cytoplasmic vesicle; Cytoplasm, cytoskeleton; Nucleus (Isoform 3)
Subcellular location (Human Protein Atlas): Cytosol; Vesicles
Pathways (Reactome):
Metabolism: NOSTRIN mediated eNOS trafficking
Gene Ontology:
Molecular function: protein binding; protein-macromolecule adaptor activity; DNA binding
Biological process: signal transduction
Cellular component: cytoplasmic vesicle; plasma membrane; endocytic vesicle membrane; cytoskeleton; nucleus
Genetic constraint (gnomAD): Loss-of-function variants: 31 observed, 28.37 expected, observed/expected ratio (o/e) 1.09, 90% interval 0.82 to 1.47. The upper end of that interval is the gene's LOEUF score, 1.47, which puts it in group 6 of 6, group 1 being the genes least tolerant of losing a copy. Missense variants: 304 observed, 284 expected, observed/expected ratio (o/e) 1.07, 90% interval 0.97 to 1.18. Synonymous variants: 109 observed, 100.77 expected, observed/expected ratio (o/e) 1.08, 90% interval 0.93 to 1.27.
Homologues: Orthologues: chimpanzee NOSTRIN (99% identical), macaque NOSTRIN (98% identical), mouse Nostrin (83% identical), pig NOSTRIN (81% identical), rat Nostrin (80% identical), guinea pig NOSTRIN (80% identical), rabbit NOSTRIN (80% identical), dog NOSTRIN (76% identical), tropical clawed frog nostrin (56% identical), zebrafish nostrin (45% identical), Caenorhabditis elegans C36E8.4 (20% identical). Paralogues in human: SH3KBP1 (13% identical), CD2AP (13% identical), MNMIP1 (9% identical).
Diseases named in the same sentence as NOSTRIN in open-access papers:
NOSTRIN is named in the same sentence as 19 diseases in open-access papers, as found by Europe PMC text mining. Sharing a sentence is not in itself a finding about the gene and the disease. The quoted sentences say what the papers report.
pancreatic cancer (3 papers, 2017 to 2021). "Overexpression of NOSTRIN, in pancreatic cancer, suppresses migration and invasion." (PMID 34797887, 2021). "Furthermore, NOSTRIN was found to be a potential negative regulator of disease aggressiveness in pancreatic cancer and CYBRD1 was identified as part of an iron regulatory gene signature that predicts outcome in BC." (PMID 28122328, 2017).
alcoholic hepatitis (1 paper, 2024). Acute hepatitis resulting from ingestion of alcohol. "NOSTRIN may be involved in preeclampsia and portal hypertension associated with alcoholic hepatitis or cirrhosis, conditions in which high levels of NOSTRIN mRNA and protein have been associated with decreased eNOS activity." (PMID 39769167, 2024).
autoimmune disease (1 paper, 2023). A disorder resulting from loss of function or tissue destruction of an organ or multiple organs, arising from humoral or cellular immune responses of the individual to their own tissue constituents. "NOSTRIN connects to another nitric oxide gene, NOS3, RNF115 to the RAS oncogene family member RAB7A, while SPRR2A connects with EVPL (associated with squamous cell cancer and autoimmune disease)." (PMID 38030619, 2023).
colon cancer (1 paper, 2022). "Previous reports on association of NOSTRIN with Cdk1/cdc2 leading to inhibition of cell cycle progression prompted our investigation on effect of NOSTRIN in regulating stemness of colon cancer cells using colonosphere formation assay." (PMID 35642021, 2022). "Ability of NOSTRIN to down-regulate EMT-associated genes led to investigation on NOSTRIN’s impact in regulating the colon cancer cells to undergo malignant transformation." (PMID 35642021, 2022). "Anti-angiogenic potentials of NOSTRIN in endothelial cells, its high abundance in colon and its role in negatively regulating pancreatic ductal cancer aggressiveness prompted our investigation on association of NOSTRIN expression with colon cancer aggressiveness." (PMID 35642021, 2022). "Our data on NOSTRIN’s ability to decrease the proliferative potential of HCT116 colon cancer is rather intriguing." (PMID 35642021, 2022). "Significant decrease in NOSTRIN expression was found with initiation and progression of advanced colon cancer disease stages." (PMID 35642021, 2022). "Association of NOSTRIN expression with aggressiveness of colon cancer cell lines, the genetic profile of EMT regulated by NOSTRIN in CRC cells as well as NOSTRIN’s ability in regulating stemness of CRC are yet to be elucidated." (PMID 35642021, 2022). "Physical interaction of NOSTRIN with Cdk1 was therefore, tested in colon cancer cells using immunoprecipitation with anti-Cdk1 (Cdc2) antibody followed by western blotting using anti-NOSTRIN antibody." (PMID 35642021, 2022). "Our further investigations focused on delineating the function of NOSTRIN in affecting colon cancer by over-expressing it in the aggressive HCT116 cell line." (PMID 35642021, 2022). "NOSTRIN over-expression thus seemed to suppress overall molecular signatures of EMT in colon cancer cells." (PMID 35642021, 2022). "NOSTRIN curbed the invasion ability of colon cancer cells towards chemo-attractant." (PMID 35642021, 2022). "Thus, interaction between NOSTRIN and Cdk1 indicated a plausible mechanism behind increased inhibitory effect on Cdk1 and the proliferative potentials of colon cancer cells." (PMID 35642021, 2022). "Thus, NOSTRIN-mediated decrease in STAT3 expression could be just another step towards reduced colon cancer aggressiveness." (PMID 35642021, 2022). "Our data on human patient samples established a negative correlation between NOSTRIN expression and advanced disease stages of colon cancer." (PMID 35642021, 2022). "Interestingly, our data demonstrated that NOSTRIN over-expression not only suppressed EMT program, but it also led to reduction in colonosphere forming ability and cancer stem cell marker expression in the colon cancer cells." (PMID 35642021, 2022).
colorectal cancer (1 paper, 2022). A primary or metastatic malignant neoplasm that affects the colon or rectum. "Taken together, our findings demonstrate high NOSTRIN expression can reduce aggressiveness of colorectal cancer (CRC) cells through attenuation in the EMT programme and their metastatic potentials." (PMID 35642021, 2022). "Owing to its abundance in colon and its known functions, we sought to investigate the role of NOSTRIN in regulating colorectal cancer." (PMID 35642021, 2022). "The findings illustrated in this study have broad biological implications, as enhanced NOSTRIN expression leading to compromised EMT and decreased stemness of cancer cells might inhibit tumorigenesis and colorectal cancer progression." (PMID 35642021, 2022). "However, there are no reports directly linking NOSTRIN with colorectal cancer." (PMID 35642021, 2022).
COVID-19 (1 paper, 2025). A disease caused by infection with severe acute respiratory syndrome coronavirus 2. "NOSTRIN downregulation in COVID-19 reduces nitric oxide production, which could enhance endothelial dysfunction and inflammation." (PMID 41227320, 2025).
pancreatic adenocarcinoma (1 paper, 2022). "Although the relevance of decreased NOSTRIN expression with disease progression in pancreatic adenocarcinoma has been well documented, role of NOSTRIN in CRC has not been reported despite its abundance in colon." (PMID 35642021, 2022).
pancreatic ductal adenocarcinoma (1 paper, 2022). An infiltrating adenocarcinoma that arises from the epithelial cells of the pancreas. "Interestingly, NOSTRIN was identified as one of the 36 gene signatures representing prognostic predictor of clinical outcome in pancreatic ductal adenocarcinoma (PDAC), wherein NOSTRIN down-regulation was associated with poor outcome." (PMID 35642021, 2022). "NOSTRIN expression was inversely related to survival of pancreatic ductal adeno-carcinoma patients." (PMID 35642021, 2022).
SARS-CoV infection (1 paper, 2020). "Another downregulated gene in the SARS-CoV infection is nitric oxide synthase traffic inducer (NOSTRIN) so this downregulation can induce the secretion of some proinflammatory chemokines and cytokines including CCL2, CCL5, and IL-6." (PMID 32754004, 2020).
cancer (3 papers, 2021 to 2022). A tumor composed of atypical neoplastic, often pleomorphic cells that invade other tissues. "NOSTRIN’s ability to sequester eNOS and consequently its dampening effect on NO production by endothelial cells has been implicated in cancer progression." (PMID 35642021, 2022). "Interaction of NOSTRIN with Cdk1 is associated with increased inhibitory Cdk phosphorylation thereby restricting cancer cell proliferation." (PMID 35642021, 2022). "Increased NOSTRIN expression leads to decreased stemness of cancer cells." (PMID 35642021, 2022). "NOSTRIN’s impact on migration potential of the cancer cells was assessed by scratch wound assay." (PMID 35642021, 2022). "We, therefore, argued that NOSTRIN might possess anti-cancer properties in CRC cells." (PMID 35642021, 2022). "OC-X treatments also caused surge upregulation of several important biomarkers within each cancer progression stage, including UCP1, NOSTRIN, SCGB3A1, ENG, EPAS1, SFTPD, and BMP4." (PMID 34069906, 2021). "The expression of four DEGs (C2orf40, NOSTRIN, NFX3, and TRPV2) has been associated with normal lung function, but they have no experimental evidence of their deregulation in cancer, or of their association with the acquisition of the hallmarks of cancer." (PMID 36101460, 2022).
tumor (3 papers, 2014 to 2022). "Conversely, B3GNT1, NOSTRIN and CADPS followed a reverse trend with down-regulation associated with poor outcome, thus suggesting a tumour suppressor role." (PMID 25587357, 2014).
cardiovascular disease (1 paper, 2023). "Consistently, we found that Pep2-8 activates Nitric Oxide Synthase Trafficking (NOSTRIN) that is implicated as protective against cardiovascular disease, and inhibits several other pathways regarded as deleterious including synthesis of lipid, systemic autoimmune syndrome and migration of cells." (PMID 37284459, 2023).
NOSTRIN also shares sentences with these, for which no sentence is quoted: Cirrhosis (1 paper); endothelial dysfunction (1); gastric cancer (1); infection (1); portal hypertension (1); preeclampsia (1); squamous cell carcinoma (1).